FTO (FTO alpha-ketoglutarate dependent dioxygenase)
Description:
RNA demethylase that mediates oxidative demethylation of different RNA species, such as mRNAs, tRNAs and snRNAs, and acts as a regulator of fat mass, adipogenesis and energy homeostasis. Specifically demethylates N(6)- methyladenosine (m6A) RNA, the most prevalent internal modification of messenger RNA (mRNA) in higher eukaryotes. M6A demethylation by FTO affects mRNA expression and stability. Also able to demethylate m6A in U6 small nuclear RNA (snRNA). Mediates demethylation of N(6),2'-O-dimethyladenosine cap (m6A(m)), by demethylating the N(6)- methyladenosine at the second transcribed position of mRNAs and U6 snRNA. Demethylation of m6A(m) in the 5'-cap by FTO affects mRNA stability by promoting susceptibility to decapping. Also acts as a tRNA demethylase by removing N(1)-methyladenine from various tRNAs. Has no activity towards 1-methylguanine. Has no detectable activity towards double-stranded DNA. Also able to repair alkylated DNA and RNA by oxidative demethylation: demethylates single-stranded RNA containing 3-methyluracil, single-stranded DNA containing 3-methylthymine and has low demethylase activity towards single-stranded DNA containing 1-methyladenine or 3-methylcytosine. Ability to repair alkylated DNA and RNA is however unsure in vivo. Involved in the regulation of fat mass, adipogenesis and body weight, thereby contributing to the regulation of body size and body fat accumulation. Involved in the regulation of thermogenesis and the control of adipocyte differentiation into brown or white fat cells. Regulates activity of the dopaminergic midbrain circuitry via its ability to demethylate m6A in mRNAs (By similarity). Plays an oncogenic role in a number of acute myeloid leukemias by enhancing leukemic oncogene-mediated cell transformation: acts by mediating m6A demethylation of target transcripts such as MYC, CEBPA, ASB2 and RARA, leading to promote their expression.
Synonyms: KIAA1752; MGC5149; ALKBH9; IFEX9; BMIQ14; GDFD
Tractability: Small molecule: a drug acting on it is in phase 2 or 3 trials; a structure with a bound ligand is known; a high-quality ligand is known. PROTAC: ubiquitination databases record sites on it; its protein half-life has been measured; a small molecule that binds it is known.
Target class: Enzyme; Oxidoreductase
Chemical probes: FB23-2
Safety:
Unwanted effects reported when the protein is acted on. In parentheses: how it was acted on, where the effect was seen, and who reports it.
alcoholism (source: ClinPGx)
drug toxicity (source: ClinPGx)
hypercholesteremia (source: ClinPGx)
leukopenia or neutropenia (source: ClinPGx)
reduction in HDL-C (source: ClinPGx)
thiopurine-induced Leukopenia (source: ClinPGx)
Gene: Protein-coding gene on chromosome 16 (53,701,692 to 54,158,512, forward strand). Ensembl gene ENSG00000140718.
Subcellular location: Nucleus; Nucleus speckle; Cytoplasm
Subcellular location (Human Protein Atlas): Cytosol; Vesicles
Pathways (Reactome):
DNA Repair: Reversal of alkylation damage by DNA dioxygenases
Gene Ontology:
Molecular function: broad specificity oxidative DNA demethylase activity; ferrous iron binding; mRNA N6-methyladenosine dioxygenase activity; oxidative RNA demethylase activity; tRNA demethylase activity; 2-oxoglutarate-dependent dioxygenase activity
Biological process: DNA alkylation repair; mRNA destabilization; regulation of brown fat cell differentiation; regulation of lipid storage; RNA repair; snRNA processing; adipose tissue development; regulation of multicellular organism growth; regulation of respiratory system process; regulation of white fat cell proliferation; temperature homeostasis
Cellular component: cytoplasm; cytosol; nuclear speck; nucleus; nucleoplasm
Genetic constraint (gnomAD): Loss-of-function variants: 42 observed, 58.81 expected, observed/expected ratio (o/e) 0.71, 90% interval 0.56 to 0.92. The upper end of that interval is the gene's LOEUF score, 0.92, which puts it in group 3 of 6, group 1 being the genes least tolerant of losing a copy. Missense variants: 529 observed, 615.36 expected, observed/expected ratio (o/e) 0.86, 90% interval 0.8 to 0.92. Synonymous variants: 195 observed, 224.08 expected, observed/expected ratio (o/e) 0.87, 90% interval 0.77 to 0.98.
Homologues: Orthologues: chimpanzee FTO (98% identical), macaque FTO (97% identical), rabbit FTO (90% identical), dog FTO (90% identical), guinea pig FTO (87% identical), mouse Fto (86% identical), pig FTO (85% identical), rat Fto (84% identical), tropical clawed frog fto (52% identical), zebrafish fto (47% identical).
Diseases named in the same sentence as FTO in open-access papers:
FTO is named in the same sentence as 389 diseases in open-access papers, as found by Europe PMC text mining. Sharing a sentence is not in itself a finding about the gene and the disease. The quoted sentences say what the papers report.
Obesity (1,528 papers, 2007 to 2026). Accumulation of substantial excess body fat. "The interactions between the FTO (Fat Mass and Obesity‐Associated Gene), TCF7L2 (Transcription Factor 7‐Like 2), and APOE (Apolipoprotein E) genes and nutrients play a crucial role in the metabolic pathways that determine disease risk." (PMID 41567168, 2026). "The fat mass and obesity-associated (FTO) gene rs9939609 polymorphism has been consistently associated with obesity risk across diverse populations." (PMID 42252861, 2026). "The fat mass and obesity-associated (FTO) protein, a pivotal player in m6A demethylation, has been linked to metabolic disorders such as diabetes and obesity." (PMID 41509912, 2026). "Fat mass and obesity-associated (FTO) protein plays a critical role in N6-methyladenosine (m6A) demethylation, linked to metabolic disorders such as diabetes and obesity." (PMID 41509912, 2026). "For example, obesity and insulin resistance are two key components of the metabolic syndrome and have been associated with genetic variations in the FTO (fat mass and obesity‐associated) gene." (PMID 41567168, 2026). "Through consensus feature selection across multiple models, the m6A methylation regulator fat mass and obesity-associated protein (FTO) was identified as a key biomarker." (PMID 41789088, 2026). "The fat mass and obesity-associated gene (FTO) has been shown to play a critical role in fat deposition in both humans and livestock." (PMID 42193912, 2026). "From a biological perspective, it reflects the transmission of obesity-susceptible genes (e.g. FTO, MC4R) that regulate energy homeostasis, appetite control, and adipocyte differentiation." (PMID 41543512, 2026). "It appears that the TT genotype in the FTO rs9939609 gene variation in Asians has a lower risk of obesity in this study." (PMID 39981080, 2025). "Certain FTO gene variants, like the rs9939609 SNP, have been shown to increase the likelihood of developing obesity, particularly in individuals of European descent." (PMID 41228239, 2025). "The SNP rs9939609 (T/A) in intron 1 of the FTO gene is one of the most extensively studied genetic variants associated with obesity." (PMID 40626223, 2025). "In South Asian populations, the association between FTO polymorphisms and obesity has been studied, with results indicating a significant correlation between the A-allele and increased adiposity measures." (PMID 40630163, 2025). "Background/Objectives: The fat mass and obesity-associated (FTO) protein demethylates nuclear N6-Methyladenosine (m6A) on mRNA, facilitates tumor growth, and contributes to therapeutic resistance in multiple cancer types." (PMID 40722726, 2025). "The highest frequency of the obesity-risk allele AA of the FTO gene was observed in MUHO, MHO, MUNW, and MHNW, respectively." (PMID 40662170, 2025). "The association between the FTO rs9939609 polymorphism and obesity has been shown to depend on dietary macronutrient intake in several European cohorts." (PMID 41190148, 2025). "Specifically, FTO polymorphisms have been linked to increased obesity risk and altered eating behaviors, while MC4R variants can influence appetite and satiety." (PMID 41228239, 2025). "Important genes associated with fat and obesity metabolism were located on CHI18 (23 Mb), including the Iroquois Homeobox 3 (IRX3) gene, which acts as a regulator of energy metabolism and is linked to pathways involving the FTO obesity variant mechanism." (PMID 39944650, 2025). "The FTO gene, first identified in 2011, is associated with obesity and is highly expressed in adipose tissue and the hypothalamus." (PMID 40094566, 2025). "The fat mass and obesity-associated (FTO) gene, a susceptibility gene for obesity, is linked to the severity of NAFLD, exhibiting high expression in fat and liver tissues." (PMID 40365443, 2025). "Studies that have passed the selection and been included in the systematic review of FTO rs9939609 genotype variants and risk of obesity in multiethnic Asians." (PMID 39981080, 2025).
Obesity (continued). "This study aimed to assess the interactions between single nucleotide polymorphism (SNP) rs9939609 of the FTO gene, anthropometric indices, and BC risk among pre- and post-menopause women with overweight/obesity in Pakistan." (PMID 40630163, 2025). "The fat mass and obesity-associated protein (FTO) have been substantiated to have pivotal associations with obesity and m6A methylation in previous studies." (PMID 40316995, 2025). "In a Spanish cohort of children and adolescents, an interaction was observed between the consumption of SFA (percentage of total energy) and PUFA: SFA ratio and obesity risk linked to the rs9939609 SNP of the FTO gene." (PMID 41190148, 2025). "The Fat mass and obesity-associated protein (FTO), a genetic variant associated with obesity, significantly impact the energetic metabolism of mechanical tumors." (PMID 39820532, 2025). "In this study, we illustrate that KYNA influences the methylation status of the Hippo signalling pathway by enhancing the expression of the fat mass and obesity-associated gene (FTO)." (PMID 40277037, 2025). "The FTO gene, particularly the intronic variant rs9939609, has emerged as the most extensively researched locus due to its established influence on obesity susceptibility and energy homeostasis regulation." (PMID 41226372, 2025). "The fat mass and obesity-associated gene (FTO) has been examined as a significant determinant of body weight and postoperative recovery." (PMID 41226372, 2025). "A recent study demonstrated that polygenic scores, derived from well-established obesity-associated loci such as FTO (Fat Mass and Obesity Associated) and MC4R, interact with lifestyle behaviors." (PMID 41009961, 2025). "The FTO gene is a novel gene, and SNPs in FTO have been linked to an increased risk of obesity in genome-wide association studies (GWAS)." (PMID 40630163, 2025). "Srivastava, Zhang, Melén,26 Lourenço,27 Granell, Loos 29 and their colleagues studied the FTO gene, and all found it related to a higher risk of obesity." (PMID 39159917, 2025). "Because of the prominent and well described important role of genetic variants in the m6A eraser FTO in obesity, we also genotyped all individuals with obesity for the known FTO risk variant rs9939609." (PMID 41225618, 2025). "Several potentially functional SNPs in the FTO region are associated with early onset and severe obesity in European populations." (PMID 41082226, 2025). "This study examined how dietary patterns affect health in children aged 4–7 years, especially in the presence of the fat mass and obesity associated (FTO) gene polymorphism." (PMID 40906427, 2025). "Molecular investigation showed that CXCL1 triggered KEAP1 m6A demethylation via FTO (fat mass and obesity-associated protein) up-regulation, subsequently reducing NRF2 expression to exacerbate ROS burst and mitochondrial fission." (PMID 41255573, 2025). "FTO, located on chromosome 16q12.2, is primarily associated with obesity but has also been implicated in other diseases, including metabolic and inflammatory conditions." (PMID 39980685, 2025). "“Writers” like METTL3 and METTL14 add m6A marks, “erasers” such as fat mass and obesity-associated protein (FTO), ALKBH5 remove them, and “readers” including YTHDF1, YTHDC1 recognize the marks, mediating functional outcomes." (PMID 40442779, 2025). "FTO, a fat-associated and obesity-associated protein, promotes adipogenesis, and its activity correlates with susceptibility to obesity." (PMID 40646842, 2025). "The genotype effect of variants in the fat mass and obesity associated (FTO) locus on increased body weight and fat mass (FM) has been studied extensively." (PMID 39792913, 2025). "The FTO gene, known to cause fat mass and obesity - related gene, participates in the m6A demethylation process and modulates the progression of several malignancies, including gastric cancer." (PMID 40110193, 2025).
Obesity (continued). "This study was set up to explore a possible impact of an obesity-related variant in the FTO locus, rs9939609, on homeostatic appetite control." (PMID 39792913, 2025). "The risk of obesity in humans is associated with genetic polymorphisms in the non-coding region of the FTO locus." (PMID 39981080, 2025). "RT–PCR and Western blot were used to investigate the expression of the fat mass and obesity-associated (FTO) gene." (PMID 39869517, 2025). "Findings suggested a positive association between FTO polymorphisms and overweight/obesity risk among children and adolescents." (PMID 41082226, 2025). "Several studies prior to the discovery of m6A indicated that FTO polymorphism was strongly associated with obesity in humans." (PMID 41077815, 2025). "Studies have shown that the FTO risk allele is associated with a 0.25–0.41 kg/m2 increase in BMI and 20–40% increased risk of obesity." (PMID 41190148, 2025). "Research indicates that FTO is upregulated in the brain in conditions of obesity, particularly in the hypothalamus and can be associated with leptin resistance, a condition that disrupts appetite and energy balance." (PMID 41277875, 2025). "For instance, many indications are associated with the risk of obesity with gene polymorphisms, such as FTO and MC4R, predominantly when coupled with high‐calorie diets." (PMID 41019177, 2025). "FTO has shown the largest number of variants associated with obesity and BMI, accounting for a difference of approximately 0.4 kg/m2." (PMID 41082226, 2025). "The development of plans for the prevention and therapy of obesity must be further improved because the association between the FTO rs9939609 gene variation has varying strengths depending on the genotype and population." (PMID 39981080, 2025). "Numerous genes found by GWA scans, including MC4R (melanocortin-4 receptor) and FTO (fat mass and obesity-associated), have been firmly linked to the risk of Obesity in a variety of populations." (PMID 41302083, 2025). "Building on this, obesity-associated genetic variations in the FTO gene have been shown to influence the differentiation of fat cells." (PMID 40055285, 2025). "FTO is the first gene associated with obesity susceptibility that was discovered through genome‐wide association studies (GWAS)." (PMID 40391584, 2025). "Genetic factors, particularly variations in genes associated with fat mass and obesity (e.g., FTO), expressed in the arcuate nucleus of the hypothalamus—a central area in appetite regulation—have consistently been associated with obesity." (PMID 39940332, 2025). "The Fat mass and obesity-associated (FTO) gene is an m6A demethylase belonging to the ALKB dioxygenase family." (PMID 41007963, 2025). "FTO gene rs9939609, rs1121980, rs17817449, rs8050136, rs9940128, rs8061518, rs9921255, and rs1477196 genotypes are associated with obesity, metabolic syndrome, and type 2 diabetes." (PMID 40864759, 2025). "In human samples, there is some evidence that the high-risk A allele at FTOrs9939609 leads to obesity by increasing FTO expression in human fibroblasts and blood cells." (PMID 40055326, 2025). "m6A modification on RNA can be reversed by demethylases, often referred to as “Erasers,” with Fat mass and obesity-associated protein (FTO) and AlkB homolog 5 (ALKBH5) being the two primary RNA demethylases." (PMID 41315216, 2025). "At the genetic level, the fat mass and obesity-associated gene (FTO) and the MC4R gene are among the most consistently linked with obesity through genome-wide association studies." (PMID 41423640, 2025). "FTO, a gene associated with obesity, encodes an mRNA demethylating enzyme that removes the m6Am (N6,2′-O-dimethyladenosine) cap modification, which controls mRNA stability." (PMID 40862085, 2025). "This study aims to examine the comparative risk of obesity in the FTO rs9939609 genotype in multiethnic groups in Asia, considering that obesity has become a global disease." (PMID 39981080, 2025).